PANX1 (pannexin 1)
Diseases named in the same sentence as PANX1 in open-access papers (continued):
Sharing a sentence is not in itself a finding about the gene and the disease.
breast carcinoma (continued). "Since Panx1 appeared to be a regulator of cell growth during early lactation we hypothesized that Panx1 levels may be relevant in breast cancer." (PMID 27099931, 2016). "Regardless, there is a need for further studies on the role of PANX1 in breast cancer." (PMID 27099931, 2016). "This may suggest that Panx1 functions as a tumor facilitator in breast cancer similar to that described in melanoma, albeit through different reported mechanisms." (PMID 27099931, 2016). "Nevertheless, the results to date suggest a tumor facilitating role of PANX1 in breast cancer." (PMID 27099931, 2016). "In particular, high Panx1 expression in basal-like breast cancer has been shown not only to be associated with enhanced epithelial-mesenchymal transition (EMT) but also to lead to neutrophil recruitment and the formation of a high adenosine immunosuppressive tumor microenvironment." (PMID 40978734, 2025). "Moreover, pharmacological inhibition of PANX1 reduces breast cancer metastasis in vivo." (PMID 35163442, 2022). "In addition, the key target cells of PANX1 in breast cancer TME need to be further explored." (PMID 35884429, 2022). "Moreover, it is reported that PANX1 promotes tumorigenesis in breast cancer through EMT pathway." (PMID 35911966, 2022). "Pannexin1 (PANX1), a glycoprotein that shares structural and functional features with connexins and engages in cell communication with its environment, is highly expressed in breast cancer metastatic foci; however, PANX1 contribution to metastatic progression is still obscure." (PMID 31817827, 2019). "Furthermore, this study uncovers a role for PANX1 in EMT regulation in breast cancer." (PMID 31817827, 2019). "In contrast to general belief of Panx channels in promoting cancer cell death, this paper suggests that ATP release by Panx1 suppresses deformation-induced apoptosis through P2Y receptor signalling and inhibition of Panx1 channels could reduce the efficiency of breast cancer metastasis." (PMID 29865195, 2018). "Mechanically-activated PANX1 contributes to ATP release from airway epithelia induced by air-puff stimulation, from erythrocytes induced by hypotonic cell swelling, from metastatic breast cancer cells induced by mechanical deformation, and from distended urothelial cells." (PMID 29534490, 2018). "Together, our results suggest that Panx1 is necessary for timely alveolar development following the transition from pregnancy to lactation, which may have implications extending to patients with breast cancer." (PMID 27099931, 2016). "Importantly, PANX1 expression within the mammary gland may have important implications to patients with breast cancer where increased expression of PANX1 is generally correlated with a worse clinical outcome." (PMID 27099931, 2016). "In addition, we explored potential implications of Panx1 as a biomarker in breast cancer." (PMID 27099931, 2016). "In this study, the relationship between high exATP/exADO levels and TANs was investigated to elucidate the properties of PANX1 and its ability to reshape the metabolic-immunosuppressive TME and provide new targets and strategies for breast cancer treatment." (PMID 35884429, 2022). "In breast cancer, PANX1 was overexpressed and promoted the transformation of tumor cells to the epithelial-to-mesenchymal transition (EMT) phenotype; breast cancer patients with high PANX1 expression had a poor clinical prognosis." (PMID 35884429, 2022). "In agreement with that notion, one recent study has shown that the PANX1 blocker, PBN, reduces PANX1 and β-catenin levels in breast cancer cells and suppresses their invasiveness and metastatic potential." (PMID 33647315, 2021). "Our data show that the inhibition of PANX1 channel activity, using PBN, or the deletion of the PANX1 gene in breast cancer cells, did decrease the mRNA levels of several EMT genes, thus confirming the GSEA in silico data." (PMID 31817827, 2019).
breast carcinoma (continued). "Compared to Luminal A (ER+ PR+ HER2−) breast cancer subtype, Luminal B (ER+ PR+ HER2+), TNBC and HER2-enriched subtypes showed significantly higher expression of PANX1." (PMID 31817827, 2019). "Pharmacological inhibition of PANX1, in MDA-MB-231 and MCF-7 breast cancer cells, or genetic ablation of PANX1, in MDA-MB-231 cells, reverted the EMT phenotype, as evidenced by decreased expression of EMT markers." (PMID 31817827, 2019). "PANX1 downregulation led to a reduction in the mRNA levels of the hypoxia transcription factor and marker, HIF-1α in breast cancer cells." (PMID 31817827, 2019). "We have evaluated the contribution of PANX1 expression in a collection of breast cancer (BRCA) RNA-seq dataset available in The Cancer Genome Atlas (TCGA) database and correlated PANX1 expression with overall survival (OS)." (PMID 31817827, 2019). "Moreover, PANX1 channel inhibition or gene ablation down-regulated EMT pathway genes and reduced the metastatic potential of breast cancer cells." (PMID 37056395, 2023). "In addition to its anti-inflammatory actions, beneficial effects of 10Panx1 were shown in Panx1-mediated platelet aggregation, α-adrenergic vasoconstriction, Panx1-related HIV replication and breast cancer metastasis in mice." (PMID 36438559, 2022). "Moreover, the coexpression of PANX1 and MPO in basal-like breast cancer paraffin-embedded surgical specimens was also observed using immunofluorescence." (PMID 35884429, 2022). "This could be because inhibiting P2X4R alone is not sufficient enough to affect PCa apoptosis, as has been shown for breast cancer, where P2X4R modulates cell death via coordinating with other receptors/signalling such as the P2X7R and Pannexin-1 channel." (PMID 33233569, 2020). "PANX1 mRNA levels are significantly higher in breast cancer patient tissues than in the normal non-cancerous adjacent tissues." (PMID 31817827, 2019). "Analysis showed that PANX1 gene expression levels were not age-dependent in breast cancer tissue (p = 0.904) or in adjacent non-cancer breast tissue (p = 0.892)." (PMID 31817827, 2019). "Decreased metastatic potential of breast cancer cells with diminished PANX1 activity prompted us to assess, using Real-Time Cell Analysis (RTCA), the invasive capacity of MDA-MB-231 cells, upon PBN treatment, and that of MDA-PANX1- cells." (PMID 31817827, 2019). "In vitro models using breast cancer cell lines such as MDA-MB-231 and MCF-7, as well as transcriptomic data analyses from patient samples, revealed that pharmacological or genetic inhibition of Panx1 reverses the EMT phenotype and reduces cellular invasiveness." (PMID 40978734, 2025). "The RNA-seq data of surgical breast cancer specimens (basal-like PANX1 high: n = 6; basal-like PANX1 low: n = 6; Luminal subtype: n = 3) suggested a higher expression of ENTPD1 and NT5E in the basal-like PANX1-high group compared to basal-like PANX1-low and Luminal group (p < 0.05)." (PMID 35884429, 2022). "Using TCGA-BRCA (n = 1083) and METABRIC (n = 1699) data, high PANX1 expression suggested poor prognosis for basal-like breast cancer in terms of overall survival (OS) (p < 0.05), while not for Luminal A, Luminal B, HER2-enriched, or normal-like subtype (PAM50 algorithm)." (PMID 35884429, 2022). "Overall, the ablating PANX1 function, pharmacologically or genetically, may constitute a novel multi-pronged therapeutic target for metastatic breast cancer by reverting EMT and decreasing the metastatic ability and invasiveness of breast cancer cells." (PMID 31817827, 2019). "Interestingly, the effect of PANX1 was similar in breast cancer cells of the basal (MDA-MB-468) and claudin-low molecular subtype (MDA-MB-231, BT-549), suggesting that this novel role for PANX1 may be seen in multiple breast cancer subtypes." (PMID 27099931, 2016). "In addition, PANX1 mRNA expression was correlated with negative clinical outcomes in patients with breast cancer using in silico arrays." (PMID 27099931, 2016).
melanoma (31 papers, 2014 to 2026). A malignant, usually aggressive tumor composed of atypical, neoplastic melanocytes. "By contrast, upregulation of PANX1/Panx1 levels was positively associated with human and murine melanoma progression." (PMID 35194046, 2022). "A recent study also found that the Y150F PANX1 mutation inhibited phosphorylation, N-glycosylation, as well as affecting the large-pore channel structure and function of PANX1 in melanoma." (PMID 34796785, 2021). "Similar to our observation with PANX1-deficient cells, knocking down β-catenin significantly decreased the growth rate of melanoma cells in our experimental setting, confirming the key role of β-catenin in melanoma cell homeostasis." (PMID 33647315, 2021). "We combined immunostaining for PANX1, and the melanocytic-lineage marker to identify melanoma tumor cells, Microphthalmia/Melanogenesis-associated transcription factor (MITF) with sequentially sectioned biopsies staining using hematoxylin and eosin (H&E)." (PMID 30654593, 2019). "PANX1 genetic variants were identified in tumors of melanoma patients and cancer cell lines." (PMID 40236296, 2025). "PANX1 has previously been implicated in melanoma tumorigenesis." (PMID 39560179, 2025). "Next, we validated our findings by immunofluorescence analysis in PANX1-deficient melanoma cells." (PMID 33647315, 2021). "Next, we evaluated the association of PANX1 and β-catenin in the melanoma cell environment." (PMID 33647315, 2021). "PANX1 channels have been implicated in various pathological conditions including ischemia, stroke, diabetes, epilepsy, and hypertension as well as cancers such as glioma and melanoma." (PMID 33564071, 2021). "Interestingly, the levels of both PANX1 protein and mRNA were substantially reduced in β-catenin-deficient melanoma cells." (PMID 33647315, 2021). "In addition, a mitochondrial stress test revealed that the metabolism of PANX1-deficient cells was impaired, indicating a role for PANX1 in the regulation of the melanoma cell metabolic profile." (PMID 33647315, 2021). "Our study indicates that PANX1 associates with β-catenin in the melanoma cell milieu." (PMID 33647315, 2021). "MITF protein was significantly reduced in PANX1-deficient melanoma cells." (PMID 33647315, 2021). "Our results suggest that high levels of PANX1 found in human melanomas at different stages of disease progression may be associated with their malignant behavior, making PANX1 a potential new target for therapeutic intervention." (PMID 30654593, 2019). "However, PANX1 has been recently implicated in the Wnt/β-catenin signaling pathway in melanoma." (PMID 33564071, 2021). "Conversely, the use of Panx1-inhibitors has shown promising results in the medication of diseases, such as neuroinflammation, melanoma and epilepsy." (PMID 41543606, 2026). "Altogether, this suggests a role for PANX1 throughout melanoma carcinogenesis, but little is known about PANX1 or PANX3 in NMSCs." (PMID 39560179, 2025). "The malignant melanoma marker β‐catenin, which was found to bind directly to the C‐terminal tail of PANX1, was also significantly decreased." (PMID 39560179, 2025). "Panx1 promotes tumor metastatic progression in multiple epithelial-derived tumors including breast, gastric, hepatocellular, testicular, melanoma, and cSCC." (PMID 40909173, 2025). "A study in melanoma cells identified that Panx1 directly interacts with β-catenin, regulating the Wnt signaling pathway and promoting tumor growth and immune evasion." (PMID 40978734, 2025). "In melanoma, Panx1 interacts with β-catenin through its N-terminus, contributing to cancer cell proliferation and tumor formation." (PMID 40909173, 2025). "We previously demonstrated that reducing PANX1 levels via shRNA knockdown or inhibiting PANX1 channels in another skin cancer reduced the malignant properties of melanoma cells such as growth and migration." (PMID 39560179, 2025).
melanoma (continued). "PANX1 channel activity in SCC‐13 cells resembles that of human melanoma cells, whereby blocking PANX1 channels also reduced melanoma cell numbers and motility." (PMID 39560179, 2025). "Previous work from our group has also showed that in melanoma, PANX1 localizes to multiple regions within the tumour structure." (PMID 39560179, 2025). "PANX1 has been proposed as a potential target to regulate anti‐tumor immunity in melanoma due to the PANX1‐mediated release of proinflammatory cytokine IL‐1β (reviewed in Ref." (PMID 38327091, 2024). "This underscores the need for research into the crosstalk between immune and tumor cells under cell‐specific PANX1 suppression/inhibition to better understand the implications of PANX1 targeting in the context of melanoma and immunotherapy." (PMID 38327091, 2024). "More recently, we showed that PANX1 is highly expressed in human melanomas, and genetic or pharmacological targeting of PANX1 decreases the tumorigenic properties of melanoma cells." (PMID 38327091, 2024). "Here, we crossed Panx1 knockout (Panx1−/−) mice with the inducible melanoma model BrafCA, PtenloxP, Tyr::CreERT2 (BPC)." (PMID 38327091, 2024). "Due to the role of PANX1 in regulating tumor growth and the immune response, we sought to evaluate the effects of the Panx1 germline deletion on melanoma progression and the tumor immune infiltration of this new hybrid mouse model." (PMID 38327091, 2024). "Mechanistically, PANX1 regulates melanoma cell growth and metabolism through direct interaction with β‐catenin and modulation of the Wnt signaling pathway." (PMID 38327091, 2024). "PANX1 pharmacological inhibition or gene knockdown slowed melanoma cell growth and significantly decreased β-catenin protein levels in melanoma cells." (PMID 38212304, 2024). "Genetic or pharmacological inhibition of the pannexin 1 (PANX1) channel‐forming protein is known to decrease melanoma cell tumorigenic properties in vitro and ex vivo." (PMID 38327091, 2024). "In this work, we crossed the global Panx1−/− mouse strain with the inducible melanoma model BrafCA/+, PtenLoxP/Loxp, Tyr::CreERT2 (abbreviated here as BPC) that harbors two known oncogenic driver mutations." (PMID 38327091, 2024). "We have previously demonstrated that PANX1 expression correlates with tumor cell aggressiveness in isogenic mouse melanoma cell lines, and its knockdown reduces melanoma tumor size and metastasis to the liver in chick chorioallantoic membrane (CAM) xenografts." (PMID 38327091, 2024). "Current literature implicates PANX1 with WNT/β-catenin signaling through the physical interaction of PANX1 with β-catenin in melanoma cells." (PMID 38212304, 2024). "To explore the in vivo effects of the Panx1 global deletion on melanoma progression, we crossed BrafCA/+, PtenLoxP/Loxp, Tyr::CreERT2 (BPC) mice with the global Panx1 knockout (Panx1−/−, Panx1KO) mouse line, reported on Ref." (PMID 38327091, 2024). "Blocking PANX1 channels reduced ATP release, as well as the growth and tumorigenic properties of human melanoma cells." (PMID 37056395, 2023). "Blocking or reducing PANX1 in melanoma cells decreases the levels of β-catenin and suppresses β-catenin transcriptional activity." (PMID 33647315, 2021). "The effect of shRNA knockdown (KD) of β-catenin on the expression of PANX1 in melanoma cells was evaluated in A375-P cells." (PMID 33647315, 2021). "Our findings provide a mechanistic insight into the role of PANX1 in regulation of cellular processes, such as proliferation, migration, and invasion during melanoma progression." (PMID 33647315, 2021). "Currently, our understanding of the mechanisms through which PANX1 regulates cellular processes and the metabolic profile of melanoma cells is very limited." (PMID 33647315, 2021). "The top three genes with the highest rates of PANX1 gene alterations were present in melanoma (4.95% of 444 cases), ovarian epithelial tumor (4.28% of 584 cases), and endometrial carcinoma (5.58% of 586 cases)." (PMID 34796785, 2021).
melanoma (continued). "We have shown that the abundance of β-catenin decreases substantially upon PANX1 depletion from both mouse and human melanoma cells." (PMID 33647315, 2021). "Analogous to our observations with PANX1 KO cells, the abundance of β-catenin was significantly reduced in PANX1 knockdown melanoma cells." (PMID 33647315, 2021). "Further, we propose that PANX1 likely contributes to the stability of β-catenin protein in melanoma cells through modulation of β-catenin protein levels and regulates β-catenin transcriptional activity in these cells." (PMID 33647315, 2021). "Overall, our findings suggest that long-term exposure to PANX1 blockers reduces PANX1 and β-catenin proteins and changes their subcellular localization in melanoma cells." (PMID 33647315, 2021). "It is likely that PANX1 regulates the metabolic profile of melanoma cells through modulation of Wnt/β-catenin signaling." (PMID 33647315, 2021). "To investigate the effect of PANX1 on β-catenin function in melanoma cells, we generated PANX1 knockout (PANX1 KO) A375-P and A375-MA2 cells using the CRISPR/Cas9 system." (PMID 33647315, 2021). "We postulated that PANX1 regulates melanoma cell metabolic profile, proliferation, and migration in part through cross talk with the Wnt signaling pathway." (PMID 33647315, 2021). "There is growing interest in investigating the role of PANX1 in the regulation of cellular processes, such as proliferation, migration, differentiation, and invasion during melanoma tumorigenesis." (PMID 33647315, 2021). "Pannexin1 (PANX1), a member of the pannexin family of channel-forming glycoproteins, regulates cellular processes in melanoma cells including proliferation, migration, and invasion/metastasis." (PMID 33647315, 2021). "Reciprocal analysis revealed that endogenous PANX1 specifically co-IP with endogenous β-catenin from 131/4-5B1 human melanoma cells." (PMID 33647315, 2021). "Taken together, our data show that PANX1 directly interacts with β-catenin to modulate growth and metabolism in melanoma cells." (PMID 33647315, 2021). "The interaction between calmodulin and PANX1 in melanoma cells represents an additional layer of complexity in the modulation of Ca2+ signaling through PANX1." (PMID 33647315, 2021). "Incubation of highly invasive 131/4-5B1 melanoma cells with either PBN or SPL markedly reduced cytoplasmic levels of both PANX1 and β-catenin." (PMID 33647315, 2021). "We observed that, similar to melanoma, mRNA expression of PANX1 significantly correlates with that of β-catenin." (PMID 33647315, 2021). "We assessed several human melanoma cell lines with transcriptional profiles similar to melanoma tumors for their PANX1 expression." (PMID 33647315, 2021). "Using pharmacological blockers to impair PANX1 channel function resulted in a significant reduction in the tumorigenic properties of the melanoma cells." (PMID 30654593, 2019). "In vitro tests had previously indicated that a knockdown of Panx1 in mouse melanomas reverted the cells to a more melanocytic-like phenotype with reduced tumorigenic properties." (PMID 30654593, 2019). "Using PANX1 channel blockers as well as shRNA vectors to reduce PANX1 function, we were able to reduce melanoma cell growth and migration, and significantly decrease primary tumor growth in a xenograft model." (PMID 30654593, 2019). "Immunofluorescence microscopy analysis from all melanoma biopsies examined was consistent with our immunoblot data, demonstrating individual variation in PANX1 levels." (PMID 30654593, 2019). "To evaluate the translational potential of our findings, we first evaluated the presence of PANX1 in human melanoma samples." (PMID 30654593, 2019). "This is consistent with reports of high PANX1 levels in other cancer types and in mouse melanomas, and would make it possible to target this protein in primary tumors as well as in advanced metastatic melanoma." (PMID 30654593, 2019).